RNU6-435P (RNA, U6 small nuclear 435, pseudogene)
Gene: Small nuclear RNA gene on chromosome 18 (24,218,300 to 24,218,404, forward strand). Ensembl gene ENSG00000206766.
Homologues: Orthologues: chimpanzee U6 (100% identical), macaque U6 (94% identical). Paralogues in human: RNU6-1145P (90% identical), RNU6-1316P (90% identical), RNU6-38P (89% identical), RNU6-1336P (88% identical), RNU6-20P (88% identical), RNU6-35P (88% identical), RNU6-434P (88% identical), RNU6-1031P (87% identical), RNU6-1124P (87% identical), RNU6-16P (87% identical), RNU6-17P (87% identical), RNU6-18P (87% identical), and 1288 more.